MBTPS2 (membrane bound transcription factor peptidase, site 2)
Description:
Zinc metalloprotease that mediates intramembrane proteolysis of proteins such as ATF6, ATF6B, SREBF1/SREBP1 and SREBF2/SREBP2. Catalyzes the second step in the proteolytic activation of the sterol regulatory element-binding proteins (SREBPs) SREBF1/SREBP1 and SREBF2/SREBP2: cleaves SREBPs within the first transmembrane segment, thereby releasing the N-terminal segment with a portion of the transmembrane segment attached. Mature N-terminal SREBP fragments shuttle to the nucleus and activate gene transcription. Also mediates the second step in the proteolytic activation of the cyclic AMP-dependent transcription factor ATF-6 (ATF6 and ATF6B). Involved in intramembrane proteolysis during bone formation. In astrocytes and osteoblasts, upon DNA damage and ER stress, mediates the second step of the regulated intramembrane proteolytic activation of the transcription factor CREB3L1, leading to the inhibition of cell-cycle progression.
Synonyms: S2P; BRESEK; IFAP; KFSD; KFSDX; OI19; OLMSX
Tractability: Antibody: UniProt predicts a signal peptide or a membrane-spanning region. PROTAC: ubiquitination databases record sites on it; its protein half-life has been measured.
Gene: Protein-coding gene on chromosome X (21,839,610 to 21,885,423, forward strand). Ensembl gene ENSG00000012174.
Subcellular location: Membrane; Cytoplasm; Golgi apparatus membrane
Subcellular location (Human Protein Atlas): Cytosol; Mitochondria; Nucleoplasm
Pathways (Reactome):
Cellular responses to stimuli: ATF6 (ATF6-alpha) activates chaperones; ATF6B (ATF6-beta) activates chaperones; CREB3 factors activate genes
Metabolism: Regulation of cholesterol biosynthesis by SREBP (SREBF)
Transport of small molecules: Assembly of active LPL and LIPC lipase complexes
Gene Ontology:
Molecular function: metalloendopeptidase activity; transcription regulator activator activity
Biological process: bone maturation; membrane protein intracellular domain proteolysis; positive regulation of cholesterol biosynthetic process; positive regulation of transcription by RNA polymerase II; protein maturation; response to endoplasmic reticulum stress; ATF6-mediated unfolded protein response; cholesterol metabolic process; endoplasmic reticulum unfolded protein response; regulation of cholesterol biosynthetic process; proteolysis
Cellular component: cytoplasm; Golgi membrane; membrane
Gene-disease validity (ClinGen):
ClinGen rates the evidence that MBTPS2 causes each of these diseases.
IFAP syndrome 1, with or without BRESHECK syndrome (X-linked): Definitive.
Homologues: Orthologues: chimpanzee MBTPS2 (99% identical), rabbit MBTPS2 (99% identical), dog MBTPS2 (99% identical), mouse Mbtps2 (97% identical), guinea pig MBTPS2 (93% identical), tropical clawed frog mbtps2 (66% identical), rat Yy2 (63% identical), zebrafish mbtps2 (60% identical), Caenorhabditis elegans Y56A3A.2 (31% identical), Drosophila melanogaster S2P (30% identical).
Diseases named in the same sentence as MBTPS2 in open-access papers:
MBTPS2 is named in the same sentence as 54 diseases in open-access papers, as found by Europe PMC text mining. Sharing a sentence is not in itself a finding about the gene and the disease. The quoted sentences say what the papers report.
IFAP syndrome (13 papers, 2011 to 2026). "Hemizygous pathogenic variants in MBTPS2 located at Xp22.12 cause IFAP syndrome, which is characterized by the triad of ichthyosis, alopecia and photophobia." (PMID 41980932, 2026). "Here we identified a hemizygous intronic variant in MBTPS2 (NM_015884: c.970+5G>A) in a patient with alopecia, follicular keratinization, developmental delay and epilepsy which were compatible with IFAP syndrome." (PMID 41980932, 2026). "IFAP syndrome is an another close differential, though it results from a mutation in the MBTPS2 gene and lacks both keratoderma and hearing loss." (PMID 41446690, 2026). "KFSDX and ichthyosis follicularis with atrichia and photophobia (IFAP) syndrome are allelic and result from mutations in a zinc metalloprotease (MBTPS2) that is important for cholesterol homeostasis." (PMID 39205768, 2024). "Ichthyosis follicularis, atrichia, and photophobia syndrome (IFAP syndrome) is a rare, X‐linked disorder caused by pathogenic variants in membrane‐bound transcription factor protease, site 2 (MBTPS2)." (PMID 34655156, 2022). "By linkage analysis and sequencing of the candidate genes, five unrelated affected males with the IFAP syndrome were each found to harbor a missense mutation in MBTPS2." (PMID 33743732, 2021). "To date, IFAP syndrome has been found to affect 19 ethnic populations associated with 20 mutations in MBTPS2." (PMID 31215178, 2019). "Mutations in MBTPS2 were also identified as genetic basis for IFAP syndrome with BRESHECK syndrome, keratosis follicularis spinulosa decalvans syndrome (KFSD; OMIM# 308800) and an X‐linked form of Olmsted syndrome (OMIM# 300918)." (PMID 31215178, 2019). "Based on the history, clinical examination, histological findings, and MBTPS2 gene mutation, the patient was diagnosed as IFAP syndrome." (PMID 31215178, 2019). "In 2009, mutations in MBTPS2 gene located in Xp22.11‐p22.13 have been reported to cause IFAP syndrome." (PMID 31215178, 2019). "IFAP syndrome results from mutations in the gene encoding the membrane‐bound transcription factor peptidase, site 2 (MBTPS2)." (PMID 31215178, 2019). "Recently, the genetic basis of IFAP syndrome has been confirmed to be associated with mutations of the MBTPS2 (membrane‐bound transcription factor protease, site 2)." (PMID 31215178, 2019). "This study demonstrated a novel MBTPS2 mutation in a patient with IFAP syndrome and thus expands the known MBPTS2 molecular repertoire." (PMID 31215178, 2019). "IFAP syndrome is an X-linked genodermatosis with variable severity and genetic mutations that were found to imply MBTPS2 gene as causal." (PMID 25685152, 2015). "The diagnosis of the IFAP syndrome is based on the clinical features and on the presence of a mutation in the MBTPS2 gene." (PMID 21600032, 2011). "IFAP syndrome results from missense mutations in the membrane-bound transcription factor protease site 2 (MBTPS2) gene." (PMID 21600032, 2011). "Here, we present an IFAP syndrome case with a rare de novo variant in the MBTPS2 gene." (PMID 37042943, 2023). "Herein, we reported an IFAP syndrome case with a novel mutation in the MBTPS2 gene." (PMID 31215178, 2019). "Wild‐type MBTPS2 was able to induce BiP/Grp78 mRNA expression 26‐fold, whereas MBTPS2 variants associated with BRESHECK syndrome and IFAP syndrome demonstrated attenuated induction of 4.7 to 8‐fold." (PMID 34655156, 2022). "One missense mutation c.1360G>C (p.Ala454Pro) in hemizygosity was detected on the MBTPS2 gene thus confirming the diagnosis of IFAP syndrome." (PMID 25685152, 2015). "Cells expressing wild‐type MBTPS2 were able to process SREBP and induce luciferase gene expression fivefold, whereas cells expressing the MBTPS2 variants associated with BRESHECK syndrome and IFAP syndrome demonstrated attenuated induction of twofold and 3.5‐fold, respectively." (PMID 34655156, 2022).
IFAP syndrome (continued). "To date, mutations in the MBTPS2 gene have been reported to cause debilitating disorders including IFAP syndrome with or without BRESHECK, KFSD, Olmsted and most recently, OI." (PMID 33743732, 2021). "Mutations in MBTPS2 also lead to IFAP (Ichthyosis follicularis - atrichia - photophobia) syndrome with or without BRESHECK syndrome (MIM #308205, ORPHA2273)." (PMID 25886873, 2015). "The OS patient with the c.671-9 T > G mutation also presents with classic IFAP syndrome, whereas previously reported patients with the same mutation in MBTPS2 has no OS features." (PMID 25886873, 2015). "Indeed, recently a Japanese patient with IFAP syndrome carrying the c.1286G > A (p.Arg429His) mutation in MBTPS2, was not as severely affected as the patients from a German family carrying the same mutation." (PMID 21600032, 2011).
Photophobia (8 papers, 2015 to 2026). Excessive sensitivity to light with the sensation of discomfort or pain in the eyes due to exposure to bright light. "MBTPS2 missense mutations were previously identified in dermatological diseases including Ichthyosis Follicularis, Atrichia, Photophobia (IFAP), and Keratosis Follicularis Spinulosa Decalvans (KFSD)." (PMID 36586072, 2022). "At the age of 16 months, sequencing of MBTPS2 gene revealed a missense mutation c.1360G>C (p.Ala454Pro) in hemizygosity, thus validating the diagnosis of ichthyosis follicularis with alopecia and photophobia (IFAP-OMIM number 308205)." (PMID 25685152, 2015).
Olmsted syndrome (7 papers, 2013 to 2023). A hereditary palmoplantar keratoderma characterized by the combination of bilateral mutilating transgredient palmoplantar keratoderma and periorificial keratotic plaques. "The mutation of p.F464S was found in a patient with the X‐linked form of Olmsted Syndrome and the intronic mutation c.671‐9T > G of MBTPS2 was found in IFAP patient with Olmsted syndrome‐like features." (PMID 31215178, 2019). "The discussion above suggests that “nonclassical” X-linked Olmsted syndrome could be an IFAP syndrome, in which the effect of the mutation in MBTPS2 interferes with the normal functioning of TRPV3." (PMID 32566327, 2020).
BRESHECK syndrome (6 papers, 2015 to 2023). "Research exome and subsequent clinical validation was notable for a maternally inherited variant of uncertain significance in MBTPS2 (c.766G>A; (p.Val256Leu)), consistent with a possible diagnosis of BRESHECK syndrome." (PMID 34655156, 2022). "Our case expands both the genetic and phenotypic spectrum of BRESHECK syndrome to include a novel MBTPS2 variant and cytopenias, bone marrow fibrosis, and chronic diarrhea." (PMID 34655156, 2022). "Pathogenic MBTPS2 variants also cause BRESHECK syndrome, characterized by the IFAP triad plus intellectual disability and multiple congenital anomalies." (PMID 34655156, 2022). "Multiple MBTPS2 variants are causal for each of the MBTPS2‐associated syndromes; however, to date, only the Arg429His variant has been associated with BRESHECK syndrome." (PMID 34655156, 2022). "We propose that the Val256Leu MBTPS2 variant represents a second causal allele for BRESHECK syndrome with bone marrow fibrosis, cytopenias, and chronic diarrhea as new manifestations of the phenotype." (PMID 34655156, 2022). "It is possible that the BRESHECK‐associated variants localize to regions critical for proper membrane topology and MBTPS2 function, or that the amino acid substitutions associated with BRESHECK syndrome are more disruptive to MBTPS2 structure and function compared to IFAP‐associated variants." (PMID 34655156, 2022). "Here, we report a patient with BRESHECK syndrome with the novel features of chronic diarrhea, anemia, bone marrow fibrosis, hypertriglyceridemia, hypobetalipoproteinemia, and hypoalphalipoproteinemia found by research‐based exome sequencing to harbor a novel Val256Leu MBTPS2 variant." (PMID 34655156, 2022). "Depending on the specific genetic variant, male human patients carrying missense mutations in the MBTPS2 gene show mostly quite severe phenotypes, sometimes with additional developmental aberrations and/or mental retardation in addition to the skin changes termed BRESEK/BRESHECK syndrome." (PMID 27449517, 2016).
keratosis follicularis spinulosa decalvans (6 papers, 2016 to 2023). Keratosis follicularis spinulosa decalvans is a rare genodermatosis occurring during infancy or childhood, predominantly affecting males, and characterized by diffuse follicular hyperkeratosis associated with progressive cicatricial alopecia of the scalp, eyebrows and eyelashes. "Prior to its association with OI, pathogenic missense variants in MBTPS2 were described in the dermatological spectrum condition Ichthyosis Follicularis, Atrichia, and Photophobia (IFAP, OMIM 308205) and Keratosis Follicularis Spinulosa Decalvans (KFSD, OMIM 308800)." (PMID 34093655, 2021).
osteogenesis imperfecta (5 papers, 2020 to 2023). Osteogenesis imperfecta (OI) comprises a heterogeneous group of genetic disorders characterized by increased bone fragility, low bone mass, and susceptibility to bone fractures with variable severity. "We highlight the role of MBTPS2 in skin disorders and X-linked recessive form of osteogenesis imperfecta (X-OI), as these pathological states provide good examples of the diversified functions and their dysfunction in diseases." (PMID 33743732, 2021).
prostate carcinoma (5 papers, 2021 to 2024). A carcinoma that arises from epithelial cells of the prostate gland. "MBTPS2 is implicated in progressive prostate cancer and may mechanistically involve its effects on fatty acid and cholesterol metabolism." (PMID 36991255, 2023). "We have demonstrated, using an unbiased forward mutagenesis screen, that mice which harboured insertions in the Mbtps2 developed more locally advanced and metastatic prostate cancers compared to control mice." (PMID 36991255, 2023). "A more recent study has found that the knockdown of MBTPS2 expression in human prostate cancer cells impaired cholesterol synthesis and uptake and reduced the expression of key regulators of fatty acid synthesis, FASN and ACACA, through SREBP signaling." (PMID 37958642, 2023). "The HPA database suggested that C18orf25, DYNC1LI2, SYNJ1, MAPK1, and ARID4B are highly expressed in normal tissues, and CLOCK, SETD2, ZNF654, XIAP, MIS18BP1, and MBTPS2 are highly expressed in prostate cancer tissues." (PMID 36249009, 2022). "MBTPS2, a membrane-embedded zinc metalloprotease, activates signaling proteins involved in transcriptional control of sterol and the ER stress response, thus promoting the progression of prostate cancer and colorectal cancer." (PMID 38167084, 2024). "Silencing of MBTPS2 expression in LNCaP, DU145 and PC3 human prostate cancer cells reduced proliferation and colony forming growth in vitro." (PMID 36991255, 2023).
ichthyosis (4 papers, 2018 to 2026). Disorders of cornification that are characterized by visible scaling and/or hyperkeratosis of most or all of the skin. "We describe a male proband with severe ichthyosis and skeletal abnormalities and a rare de novo MBTPS2 missense variant affecting the transmembrane domain." (PMID 37042943, 2023). "Here, we describe a patient with ichthyosis, pulmonic stenosis, renal dysplasia, hypospadias, growth failure, thrombocytopenia, anemia, bone marrow fibrosis, and chronic diarrhea found by research‐based exome sequencing to harbor a novel, maternally inherited Val256Leu MBTPS2 variant." (PMID 34655156, 2022).
breast carcinoma (3 papers, 2017 to 2022). "The results showed that some of the genes related to the prognosis of breast cancer (IKBKB, ATG16L2, CLN3, MBTPS2, TSC2, and CAPN10) had a higher frequency of mutations." (PMID 34457116, 2021). "Our results showed that similar to that of YY2, the expression of Mbtps2 was downregulated in breast cancer cell lines." (PMID 28903375, 2017).
Palmoplantar keratoderma (3 papers, 2016 to 2026). Abnormal thickening of the skin of the palms of the hands and the soles of the feet. "For example, a mutation of TRPV3 or membrane‐bound transcription factor protease site 2 (MBTPS2) could lead to Olmsted syndrome, described by bilateral mutilating palmoplantar keratoderma (PPK) and periorificial keratotic plaques." (PMID 35342611, 2022). "TRPV3 regulated by mutated MBTPS2 or directly mutated TRPV3 might function in a dominant‐positive manner to increase constitutive TRPV3 activity and elevate Ca2+ in keratinocytes, leading to severe keratoderma." (PMID 35342611, 2022).
osteoporosis (2 papers, 2016 to 2024). A condition of reduced bone mass, with decreased cortical thickness and a decrease in the number and size of the trabeculae of cancellous bone (but normal chemical composition), resulting in increased fracture incidence. "This is a whole field in itself, and the question is, ‘‘what is the nosologic description of these syndromes of osteoporosis in young adult women with heterozygous variants in PLS3 or MBTPS2 or SMS’’ in their reproductive years?’’." (PMID 38942908, 2024). "Female patients with expression of heterozygous genomic variants in X-Linked PLS3, MBTPS2 and SMS may have symptomatic osteoporosis." (PMID 38942908, 2024).
acrodermatitis (1 paper, 2021). An inflammatory skin condition affecting children. "Other known examples of functional variants at position +3 or +4 in 5′-splice sites include the MKLN1:c.400+3A>C variant in dogs with lethal acrodermatitis or the MBTPS2:c.1437+4C>T variant in horses with the brindle 1 phenotype." (PMID 34680893, 2021).
dyslipidemia (1 paper, 2022). "Furthermore, this study was the first to discover that several CpG sites in genes involved in lipid metabolism (AMFR, FBXW7, INSIG1/2, MBTPS2) are associated with dyslipidemia." (PMID 36570009, 2022).
familial hypercholesterolemia (1 paper, 2021). An inheritable form of hyperlipidemia, in which there are excess lipids in the blood.
laryngeal carcinoma (1 paper, 2021). Carcinoma that arises from the laryngeal epithelium. "This suggests that EGFR and INHBA can serve as prognostic hub genes for laryngeal cancer collectively with pRS genes (CFLAR, DAPK2, TSC2, CAPN10, MBTPS2, PEX14, FADD and ST13)." (PMID 34093817, 2021).
lung carcinoma (1 paper, 2021). "Thus, a downregulation of ACSL3 observed in MBTPS2 mutant cells may alter cellular metabolism, energy production and cell survival, similar to that observed in lung cancer cells." (PMID 34093655, 2021).
metastatic disease (1 paper, 2023). "Here, we identified Mbtps2 alteration to be associated with metastatic disease in an unbiased in vivo screen and demonstrated its regulation of fatty acid and cholesterol metabolism." (PMID 36991255, 2023).
metastatic prostate carcinoma (1 paper, 2023). A carcinoma that arises from the prostate gland and has spread to other anatomic sites. "Mbtps2 was identified in our transposon-mediated in vivo screen to be associated with metastatic prostate cancer." (PMID 36991255, 2023).